APOE (apolipoprotein E)
Diseases named in the same sentence as APOE in open-access papers (continued):
Sharing a sentence is not in itself a finding about the gene and the disease.
atherosclerosis (continued). "MiR-34a has been reported to trigger ECs aging through repression of SIRT1, whereas antagonism of miR-34a reduced ECs apoptosis and the development of atherosclerosis in ApoE−/− mice." (PMID 35155600, 2021). "Our present study found that treatment with OMVs from CagA-positive H. pylori accelerated atherosclerosis plaque formation in ApoE–/– mice." (PMID 34790655, 2021). "Liraglutide, a glucagon-like peptide 1 (GLP1) receptor agonist, is known to inhibit the atherosclerosis of apoE mice and suppress the cellular behaviors of VSMCs induced by AngII." (PMID 34666623, 2021). "Despite abnormal lipoprotein levels, Dysf/ApoE double knockout mice responded to cholesterol absorption blockade with lower total cholesterol and blunted atherosclerosis." (PMID 34366880, 2021). "ATL4 reduced the macrophage infiltration and apoptosis in ApoE−/− mice with atherosclerosis in the aortic roots and thoracic aorta." (PMID 33413594, 2021). "Zhen identified a total of 28 dysregulated miRs at different stages of atherosclerosis in ApoE-/- mice fed with a Western-type diet." (PMID 34775883, 2021). "SM22α-hSIRT6/ApoE−/− mice had reduced atherosclerosis, markers of senescence and inflammation compared with littermate controls, while plaques of SM22α-hSIRT6H133Y/ApoE−/− mice showed increased features of plaque instability." (PMID 33353368, 2021). "The role of TMAO in atherosclerosis was investigated using a dietary choline supplement in ApoE−/− mice." (PMID 33401598, 2021). "The role of PKCβII in MMP expression and secretion has also been examined in atherosclerosis-prone ApoE null mice." (PMID 34276388, 2021). "It prevented atherosclerosis in ApoE−/− mouse model, and in vitro evidence supported this effect commendably, highlighting the therapeutic potential in atherosclerosis." (PMID 35069197, 2021). "To examine this, we used the well-established mouse model of atherosclerosis ApoE−/−, and crossed these to the PEA-15−/− mice to ApoE−/−/PEA-15−/− mice." (PMID 33772049, 2021). "PepE treatment inhibited atherosclerosis development by suppressing NLRP3 inflammatory pathway in HFD-fed ApoE−/− mice." (PMID 34299310, 2021). "While OGG1−/−ApoE−/− mice display elevated 8oxoG and increased atherosclerotic plaque compared to control ApoE–/– mice, VSMC specific OGG1 overexpressing SM22α-OGG1 ApoE−/− mice are protected from high-fat-diet-induced atherosclerosis." (PMID 34831061, 2021). "ApoE −/− mice develop atherosclerotic lesions in response to a cholesterol-rich diet and are widely used to study the pathogenesis of atherosclerosis." (PMID 34422919, 2021). "In a study, using PXR-humanized apolipoprotein E-deficient (huPXR∙ApoE−/−) mouse model, perinatal exposure to BPA worsened atherosclerosis in adult male huPXR∙ApoE−/− offspring." (PMID 35295127, 2021). "For instance, mtDNA damage correlates with increased atherosclerotic occlusion of coronary arteries, as well as with the extent of atherosclerosis lesions in ApoE knockout mice." (PMID 34573095, 2021). "In a subsequent study, we were able to show that suppression of SAA3 (via anti-sense oligonucleotide) in DKO mice significantly reduced atherosclerosis compared to apoE−/− mice." (PMID 34944527, 2021). "The degree of mitochondrial dysfunction, reactive oxygen species production, vascular senescence, atherosclerosis, and the number of fragmented mitochondria accompanied by Drp1 activation were all higher in ApoE KO mice than in C57BL/6 mice." (PMID 34869701, 2021). "In line with this notion, it is known that the ApoE-knock-out (KO) mouse is a model for atherosclerosis." (PMID 34721384, 2021). "While less is known about the lipid exchange properties of ApoE, ApoE-containing rHDL (ApoE-rHDL) were shown to have potential for atherosclerosis treatment, although further testing is needed." (PMID 33996741, 2021).
atherosclerosis (continued). "Treatment of mice with anti-phosphorylcholine-specific IgM diminished plaque development, and treatment with IgG from ApoE-/- mice boosted atherosclerosis, supporting the theory that IgM is helpful and IgG is harmful." (PMID 34305930, 2021). "Similar effects were shown for resveratrol, which, by changing the gut microbiota composition, decreases TMAO-mediated atherosclerosis in ApoE -/- mice." (PMID 34576810, 2021). "Although no previous studies have analyzed the effect of ERK1 deficiency on atherosclerosis in vivo, pharmacological inhibition of ERK1/2 and activation of LXR was found to synergistically decrease atherosclerotic lesions in ApoE−/− mice." (PMID 34569651, 2021). "Although ApoE−/− mice are extensively used for atherosclerosis research, there are still several limitations, and the model does not compare well to human in terms of lipid profile." (PMID 34836239, 2021). "Our study showed that nucleolin was increased in vascular smooth muscle cells in the atherosclerosis plaque of apoE‐/‐ mice." (PMID 33219625, 2021). "Our present study demonstrates that ethanol binge drinking, a risk factor for CVD, can selectively increase protein S-glutathionylation in the aorta, liver and brain of ApoE−/− mouse model of atherosclerosis." (PMID 33796575, 2021). "In contrast, a recent study suggested that IL-1ß also has beneficial effects in late-stage atherosclerosis in an ApoE−/− mouse model." (PMID 32648087, 2021). "In a study on the pathogenesis of atherosclerosis, activation of AMPK suppressed the development of atherosclerosis in ApoE-KO mice." (PMID 34830282, 2021). "Macrophage‐specific deletion of autophagy proteins has been shown to lead to an increased formation of atherosclerotic lesions and secretion of IL‐1β in vivo in an ApoE‐/‐ mouse model of atherosclerosis." (PMID 34377468, 2021). "ApoE knockout (KO) mice spontaneously develop hypercholesterolemia and atherosclerosis when fed standard chow." (PMID 34206159, 2021). "Our results showed that in 5/6 Nx ApoE–/– mice, SM protected the endothelial cells and arrested atherosclerosis to attenuate ROS-injury arising as a result of chronic kidney injury." (PMID 34679653, 2021). "We have previously observed that global deficiency of MC1-R signaling perturbs cholesterol homeostasis, increases arterial leukocyte accumulation and accelerates atherosclerosis in apolipoprotein E knockout (Apoe-/-) mice." (PMID 34868038, 2021). "Conversely, and surprisingly, the induction of HSPs after the formation of atheromas promoted the progression of atherosclerosis in ApoE−/− mice." (PMID 33782520, 2021). "An ApoE-/- knockout mice model has long been used as an atherosclerogenic model which develops atherosclerosis lesions in the middle-to-large arterial tree." (PMID 34775883, 2021). "In this study, atherosclerosis model was established in apolipoprotein E null mice (ApoE-/-) fed with high fat diet (HFD), and a highly specific small-molecule CDK9 inhibitor, LDC000067, was utilized to treat the atherosclerotic mice." (PMID 34102609, 2021). "apoE-ε3 has been thought to be the “neutral” apoE genotype; apo-ε4 was reported to be involved in the pathogenesis of atherosclerosis and Alzheimer's diseases." (PMID 34746320, 2021). "Through an intensive literature search, we established the functional implication relevant to atherosclerosis and inflammation of these differentially expressed checkpoint genes in ApoE-/- Ly6Chigh and Ly6Clow MC." (PMID 34987524, 2021).
atherosclerosis (continued). "Consistent with previous studies, our results indicate that CIH can significantly promote the progression of atherosclerosis in normal chow diet-fed ApoE-/- mice." (PMID 34504429, 2021). "Our previous studies showed that VSMC-specific SCAP knockdown prevented the development of atherosclerosis in ApoE-/- mice by activating autophagy, with a decreased vascular inflammatory response." (PMID 34094640, 2021). "Previous studies have shown that Ruminococcaceae and Lachnospiraceae were positively correlated with atherosclerotic lesion size in ApoE−/− mice, and Coriobacteriaceae was enriched in patients with symptomatic atherosclerosis." (PMID 33897472, 2021). "Female APOE*3-Leiden.CETP mice were fed a Western-type diet to induce advanced atherosclerosis, followed by an injection with a small interfering RNA targeting Proc (siProc)." (PMID 34052976, 2021). "To investigate the role of platelets in d-flow induced atherosclerosis, we examined the serial-sections of atherosclerotic plaques of the aortic arch of Ldl-r-/- or ApoE-/-mice fed high-fat diet (HFD) using immunostaining." (PMID 34815786, 2021). "In the atherosclerosis model of apoE−/− mice, vascular expression of CD44 was highest in areas prone to damage." (PMID 34335086, 2021). "To identify the exact roles of Th17 cells in all stages of atherosclerosis, we established an experimental atherosclerosis model by feeding ApoE−/− mice with HFD." (PMID 33981738, 2021). "In our research, Danlou tablets significantly relieved the pathological process of atherosclerosis in ApoE−/− mice, including decreased lipid accumulation, fibrosis formation, and inflammation responses." (PMID 34867337, 2021). "In another study, insulin-like growth factor (IGF)-1 was formulated in nanofibers/hydrogel showed atherosclerosis inhibition in vivo following sc administration in ApoE knockout mice." (PMID 34867370, 2021). "The MMP-12 inhibitor significantly reduced atherosclerotic plaque area and delay atherosclerosis development in ApoE–/– mice." (PMID 34917605, 2021). "We describe potential intermediate steps in this model, linking cholesterol, atherosclerosis, and APOE with VCID." (PMID 33841127, 2021). "While a rationale can be found in atherosclerosis (efflux of cellular lipid to APOE and HDL resulting in lower lipid burden in the vascular system), the translation of this rationale to AD can only be achieved to a very limited extent." (PMID 34977908, 2021). "We first examined the efficacy of 3C (10 mg/Kg/day) in HFD-induced atherosclerosis model in ApoE-/- mice." (PMID 33901014, 2021). "Methods and Results: An inhibitor of Grp94, HCP1, was used to investigate the role of Grp94 in oxLDL-induced VEC injury in human umbilical vein endothelial cells and atherosclerosis in apolipoprotein E−/− mice." (PMID 34938782, 2021). "At the same time, miR-17-5p is highly expressed in the PBMCs of patients with atherosclerosis and suppressing miR-17-5p can alleviate atherosclerosis in ApoE−/− mice." (PMID 34940525, 2021). "Recombinant IL-6 treatment exacerbates atherosclerosis in wild-type and atherosclerosis-prone ApoE−/− mice fed with a high-fat diet, which shows a dramatically increased lesion size." (PMID 34539804, 2021). "In an experimental animal model of atherosclerosis (ApoE−/− mice), feeding a western diet (2% high fat and 1.25% high cholesterol) increased the serum level of ox-LDL as well as the activities of GlcCer synthase and LacCer synthase." (PMID 33673027, 2021).
atherosclerosis (continued). "Another study indicated that inulin treatment improved atherosclerosis and the number of macrophages in male APOE*3-Leiden mice." (PMID 34445037, 2021). "The overexpression of human Prdx4 in ApoE‒/‒ mice highly attenuated the development of atherosclerosis by limiting the infiltration of T-lymphocytes, reducing the OS, and ameliorating necrosis." (PMID 34439492, 2021). "5-MTP administration reduced chondrogenesis and calcification in HFD-induced atherosclerosis in ApoE−/− mice and inhibited VSMC phenotypic switch to calcified chondrocytes induced by TLR2 and TLR4 activation." (PMID 34749728, 2021). "As well, the expression of miR33a-5p decreased over time in the high fat fed ApoE-/- mice in our study, which indicating down-regulation of miR33a-5p in the development of atherosclerosis." (PMID 34803487, 2021). "Another study showed significantly decreased NP (90 nm hyaluronan NP) accumulation in the aortic arch of ApoE-/- mice (where atherosclerosis naturally develops) at 12 weeks compared to 6 weeks on a Western diet." (PMID 34882722, 2021). "Apolipoprotein E (human APOE; murine ApoE) has not only been implicated in the pathogenesis of AMD, but also Alzheimer’s disease (AD) and atherosclerosis." (PMID 34210002, 2021). "In ApoE‒/‒ mice with transplanted bone marrow, hematopoietic Prdx4 overexpression was sufficient to suppress the progression of atherosclerosis." (PMID 34439492, 2021). "The results show that vascular production of 5-MTP was suppressed by HFD-induced atherosclerosis in ApoE−/− mice, which was restored by genetic deletion of TLR2." (PMID 34749728, 2021). "In this study, ApoE–/– mice were used to construct an atherosclerosis animal model after 8 weeks of HFD." (PMID 34307380, 2021). "This is similar with the results with HE staining, in which ApoE–/– mice treated with H. pylori-derived OMVs had more serious atherosclerosis than control mice." (PMID 34790655, 2021). "Methods and Results: In order to explore the effect of the physiological and continuous elimination of Ox-LDL through the liver on advanced atherosclerosis, we chose ApoE-/- mice in high-fat diet for 20 weeks." (PMID 34790037, 2021). "In apoE-/- mice, overexpression of H19 aggravated atherosclerosis progression; however, silencing of H19 protected against atherosclerosis." (PMID 34179148, 2021). "ApoE has protective effects on the progression of atherosclerosis by promoting the hepatic uptake of atherogenic lipoproteins and macrophage cholesterol efflux." (PMID 34441867, 2021). "Hyperlipidemia has been reported to accelerate lipid accumulation, atherosclerosis, and chronic inflammation in apolipoprotein E knockout (ApoE−/-) or low-density lipoprotein receptor-deficient (LDL-R−/−) mice." (PMID 34975474, 2021). "Similar to ApoE-KO/Tie2-TERF2DN-Tg mice, ApoE-KO/VEcad-TERF2DN-Tg mice showed exacerbated atherosclerosis as compared to ApoE-KO mice after 2-week of HCD feeding." (PMID 34272458, 2021). "Third, we used ApoE−/− mice fed a methionine diet to clarify the role of PCSK9 in atherosclerosis accelerated by Hcy." (PMID 34660746, 2021). "Both Oil Red O and HE staining showed that ApoE–/– mice intragastrically administered with H. pylori-derived OMVs had more serious atherosclerosis, indicating that H. pylori-derived OMVs accelerate atherosclerosis plaque formation." (PMID 34790655, 2021). "In an in vivo study, dietary intake of walnut showed a protective effect on atherosclerosis with a decrease in CD36 expression in apoE‐/‐ mice." (PMID 34136191, 2021). "As aged wild-type mice exhibit minimal atherosclerosis, ApoE−/− mice are a relevant model to study GzmB and its role in PI in the context of aging in humans." (PMID 33674592, 2021).
atherosclerosis (continued). "To evaluate the impact of agmatine on the development of atherosclerosis, we treated apoE−/− mice fed a Western high-fat diet with agmatine (20 mg per kg of body weight per day) for 16 weeks." (PMID 34639029, 2021). "Together, our results indicate that Ren/Ang-mediated elevation of BP by 20 mmHg to levels considered non-pathological in humans (120–140 mmHg) is a significant contributing factor to atherosclerosis development in an ApoE−/− preclinical model." (PMID 34445154, 2021). "Analysis of the impact of PPARα on atherosclerosis revealed that PPARα-KO on the ApoE-null background surprisingly reduced the number of atherosclerotic lesions, despite an increase in the circulating concentrations of atherogenic lipoproteins." (PMID 34360540, 2021). "ApoE-/- mice fed with a high-fat diet are widely used for miRs profiling, regulatory, and therapeutic targeting studies related to atherosclerosis." (PMID 34775883, 2021). "There were 6 samples in microarray data GSE2372, which contained three samples from WT mice and three samples from ApoE knockdown mice with atherosclerosis." (PMID 33872218, 2021). "Apolipoprotein E-knockout (apoE−/−) mice have been widely used in atherosclerosis research due to their propensity to spontaneously develop hypercholesterolemia and atherosclerotic plaques on a chow diet." (PMID 34639029, 2021). "Apolipoprotein E (ApoE) is a lipoprotein that exerts antiatherogenic effects by affecting lipoprotein metabolism directly and indirectly during the development of atherosclerosis." (PMID 33796572, 2021). "We have previously reported that AGE inhibits lipid deposition in apolipoprotein E knockout (ApoE-KO) mice, an atherosclerosis model." (PMID 34789834, 2021). "In this study, inflammation and phenotypic switching of VSMCs were observed in HFD-induced atherosclerosis in ApoE-/- mice, which were accompanied with increased CDK9 in the serum and atherosclerotic lesions where it colocalized with VSMCs." (PMID 34102609, 2021). "Intriguingly, atherosclerosis levels were significantly reduced in mice that received CD43− splenocytes from ApoE−/−CCR6+/+sIgM+/+ mice compared to those that received PBS (control)." (PMID 33679793, 2021). "In our previous study, we have found that the expression of Wnt5a is notably up-regulated in both patients with atherosclerosis and apoE-/- mice." (PMID 34326694, 2021). "Previous studies showed that chronic stress can significantly accelerate the atherosclerosis process in ApoE knock out animals." (PMID 34580342, 2021). "The pathological characteristics of ApoE−/− mice with atherosclerosis are very similar to those of humans with atherosclerosis." (PMID 34867337, 2021). "To investigate the link between elevated BP and atherosclerosis development, we injected ApoE−/− mice with AAV-Ren and AAV-Ang before switching the animals to a defined dietary regime." (PMID 34445154, 2021). "Pitavastatin reduced the LDL-C levels in stressed ApoE–/– mice and we also observed that: (a) Pitavastatin decreased the inflammatory response of the atherosclerosis by reducing the accumulation of macrophages and the expression of osteopontin proteins." (PMID 34368136, 2021). "Of note, feeding with high-fat and western-type diets accelerates the development of atherosclerosis in ApoE−/− mice." (PMID 33782520, 2021).